INPP5J (inositol polyphosphate-5-phosphatase J)
Description:
Inositol 5-phosphatase, which converts inositol 1,4,5-trisphosphate to inositol 1,4-bisphosphate. Also converts phosphatidylinositol 4,5-bisphosphate to phosphatidylinositol 4-phosphate and inositol 1,3,4,5-tetrakisphosphate to inositol 1,3,4-trisphosphate in vitro. May be involved in modulation of the function of inositol and phosphatidylinositol polyphosphate-binding proteins that are present at membranes ruffles.
Synonyms: PIB5PA; PIPP; INPP5
Tractability: Antibody: its Gene Ontology location is reachable by antibodies, with medium confidence. PROTAC: its protein half-life has been measured.
Gene: Protein-coding gene on chromosome 22 (31,122,731 to 31,134,697, forward strand). Ensembl gene ENSG00000185133.
Subcellular location: Cytoplasm
Subcellular location (Human Protein Atlas): Cytosol; Nucleoli fibrillar center
Pathways (Reactome):
Metabolism: Synthesis of IP2, IP, and Ins in the cytosol; Synthesis of IP3 and IP4 in the cytosol; Synthesis of PIPs at the plasma membrane
Gene Ontology:
Molecular function: protein binding; inositol trisphosphate phosphatase activity; inositol-1,4,5-trisphosphate 5-phosphatase activity; phosphatidylinositol-3,4,5-trisphosphate 5-phosphatase activity; inositol-1,3,4,5-tetrakisphosphate 5-phosphatase activity; inositol-polyphosphate 5-phosphatase activity; phosphatase activity; phosphatidylinositol-4,5-bisphosphate 5-phosphatase activity
Biological process: inositol phosphate metabolic process; negative regulation of microtubule polymerization; phosphatidylinositol biosynthetic process; phosphatidylinositol dephosphorylation; phosphorus metabolic process
Cellular component: cytoplasm; ruffle; cytosol; neuron projection; plasma membrane; dendritic shaft; growth cone; plasma membrane bounded cell projection
Genetic constraint (gnomAD): Loss-of-function variants: 76 observed, 79.63 expected, observed/expected ratio (o/e) 0.95, 90% interval 0.79 to 1.15. The upper end of that interval is the gene's LOEUF score, 1.15, which puts it in group 5 of 6, group 1 being the genes least tolerant of losing a copy. Missense variants: 1,229 observed, 1,297.1 expected, observed/expected ratio (o/e) 0.95, 90% interval 0.9 to 0.99. Synonymous variants: 540 observed, 532.61 expected, observed/expected ratio (o/e) 1.01, 90% interval 0.94 to 1.09.
Homologues: Orthologues: chimpanzee INPP5J (99% identical), macaque INPP5J (97% identical), dog INPP5J (88% identical), pig INPP5J (86% identical), guinea pig INPP5J (84% identical), rat Inpp5j (83% identical), mouse Inpp5j (82% identical), zebrafish inpp5ja (32% identical), zebrafish inpp5jb (29% identical), tropical clawed frog inpp5j (18% identical), Caenorhabditis elegans unc-26 (15% identical), Drosophila melanogaster CG9784 (15% identical), and 4 more. Paralogues in human: INPP5K (20% identical), INPP5B (19% identical), SYNJ2 (18% identical), OCRL (17% identical), SYNJ1 (17% identical), INPP5D (14% identical), INPPL1 (14% identical), INPP5E (12% identical), INPP5F (11% identical), FIG4 (9% identical), SACM1L (7% identical), SH2D1B (2% identical), and 1 more.
Diseases named in the same sentence as INPP5J in open-access papers:
INPP5J is named in the same sentence as 24 diseases in open-access papers, as found by Europe PMC text mining. Sharing a sentence is not in itself a finding about the gene and the disease. The quoted sentences say what the papers report.
breast carcinoma (11 papers, 2017 to 2025). "The INPP5J gene is located on chromosome 22q12 and allelic loss of this region occurs in ~30% of breast cancers." (PMID 28082369, 2017). "Research has demonstrated that both the mRNA and protein expression levels of INPP5J are markedly reduced in ovarian cancer, breast cancer, and pancreatic cancer." (PMID 41049486, 2025). "INPP5J regulates AKT1-dependent breast cancer growth and metastasis and predicts recurrence in lung adenocarcinoma." (PMID 35615380, 2022). "Significant redundancy among 5-phosphatases may also explain the lack of prevalent tumor suppressors among this family, though the recent identification of PIPP (INPP5J) as a potential tumor suppressor in breast cancer points to contexts in which individual enzymes may predominate." (PMID 29056325, 2017). "For instance, depletion of INPP5J reduces cell migration and invasion by regulating AKT1 signaling in breast cancer." (PMID 34996491, 2022). "Inositol 5-phosphatase INPP5J, a screen hit and AKT negative regulator, was a recently identified breast cancer suppressor, supporting our screen’s robustness." (PMID 31285545, 2020). "INPP5J is a negative regulator for PI3K/AKT signaling and thus may function as a tumor suppressor, which was demonstrated in breast cancer, ovarian cancer, hepatocellular carcinoma, and oesophageal squamous cell carcinoma." (PMID 32802843, 2020).
melanoma (8 papers, 2015 to 2025). A malignant, usually aggressive tumor composed of atypical, neoplastic melanocytes. "We then tested the impact of these dCas9-VprBP fusions on the transcription of INPP5J, ZNF750, and TUSC1 genes in G361 melanoma cells." (PMID 37293029, 2023). "Among the most significantly altered genes, we selected INPP5J, ZNF750, and TUSC1 for further study because their gene products are known to reduce the viability and malignant proliferation of melanoma cells." (PMID 37760992, 2023). "Among most significantly altered genes, we selected INPP5J, ZNF750, and TUSC1 for further study because their gene products are known to reduce the viability and malignant proliferation of melanoma cells." (PMID 37293029, 2023). "Copy number reduction of PTEN, INPP5J and INPP4B have been reported to be relatively common in melanoma." (PMID 33549048, 2021). "It has been noted that INPP5J suppresses PI3K/AKT signaling by reducing AKT at its hydrophobic motif site, Ser473, and was recently found to be downregulated in melanoma and esophageal squamous cell carcinoma, leading to the promotion of cell proliferation and tumorigenicity in vivo." (PMID 25849943, 2015). "Also supportive of the idea that VprBP modulates transcription at the level of initiation, dCAS9-VprBP was highly efficient in suppressing the transcription of INPP5J, ZNF750, and TUSC1 genes when guided to their promoter regions by sgRNAs in VprBP-depleted melanoma cells." (PMID 37293029, 2023).
ovarian carcinoma (4 papers, 2020 to 2025). A malignant neoplasm originating from the surface ovarian epithelium. "Especially, miR-661 was reported to contribute to the cell proliferation of ovarian cancer by inhibiting INPP5J expression." (PMID 35436983, 2022). "INPP5J protein expression was drastically decreased in human ovarian cancer cells and acted as a vital negative regulator of PI3K/Akt signaling in numerous types of human cancers." (PMID 33490259, 2020).
esophageal squamous cell carcinoma (3 papers, 2015 to 2025). Esophageal squamous cell carcinoma (ESCC) is a type of esophageal carcinoma (EC) that can affect any part of the esophagus, but is usually located in the upper or middle third. "In esophageal squamous cell carcinoma (ESCC), the elevated miR-508-3p correlates with poor survival and activated PI3K/Akt signaling by targeting inositol polyphosphate-5-phosphatase J (INPP5J), phosphatase and tensin homologue (PTEN) and inositol polyphosphate 4-phosphatase type I (INPP4A)." (PMID 26801246, 2016).
Lowe syndrome (2 papers, 2023 to 2025). "Mutations or misexpression of PI phosphatases, including INPP5J, are associated with several human genetic diseases, such as Lowe syndrome, developmental disorders, and cancers, often leading to loss of function." (PMID 39936965, 2025). "Specifically, we selected synaptojanin 1⁄2 (SYNJ1/2), INPP5E, INPP5J, oculocerebrorenal syndrome of Lowe (OCRL), INPP5B, and INPP5K, of which INPP5E/B and OCRL have already been shown to alter ciliary lipid composition." (PMID 38110903, 2023).
lymph node metastasis (1 paper, 2019). "In this study, we identified 4 coding genes associated with overall survival in LUAD patients with lymph node metastasis, namely, LDHA, ABAT, FAM117A and INPP5J, in the training set." (PMID 31015800, 2019).
osteoarthritis (1 paper, 2024). A noninflammatory degenerative joint disease occurring chiefly in older persons, characterized by degeneration of the articular cartilage, hypertrophy of bone at the margins and changes in the synovial membrane. "Additionally, curcumin can exert therapeutic effects on osteoarthritis by targeting the PIP4K2C, INPP5J, ITPKA, ITPKB, ISYNA1, and PLCH2 proteins associated with inositol phosphate metabolism." (PMID 37938371, 2024).
tumor (12 papers, 2015 to 2025). "Targeting and modulating INPP5J expression have been shown to effectively suppress tumor cell growth, indicating its potential therapeutic significance in cancer treatment." (PMID 41049486, 2025). "INPP5J is a critical tumor suppressor that primarily inhibits tumor cell proliferation through the regulation of cellular signaling pathways." (PMID 41049486, 2025). "However, it has been shown that the same family of INPP5J appears to be a tumor suppressor gene, and many inositol polyphospho-5 phosphatase family molecules can affect cell migration, adhesion and polarity (Ramos, Elong Edimo & Erneux, 2018)." (PMID 34430085, 2021).
cancer (9 papers, 2017 to 2025). A tumor composed of atypical neoplastic, often pleomorphic cells that invade other tissues. "The downregulation of Gdf3 and Inpp5j in whole blood might represent a self-protective mechanism against adipogenesis and carcinogenesis, as elevated levels of Gdf3 and Inpp5j are associated with fat deposition and cancer development, respectively." (PMID 39936965, 2025). "It remains to be investigated whether the downregulation of Inpp5j is involved in the development of any diseases, such as cancer, at the late stages of animal life." (PMID 39936965, 2025). "The termination of the PIP3 signal is mediated by lipid phosphatases such as PTEN, PIPP (INPP5J), and INPP4B, which are often found to be altered in various cancers, including CRC." (PMID 39370455, 2024).
INPP5J also shares sentences with these, for which no sentence is quoted: triple-negative breast carcinoma (2 papers); Allergy (1); Alzheimer disease (1); breast tumors (1); colorectal cancer (1); cutaneous squamous cell carcinoma (1); genetic diseases (1); hepatocellular carcinoma (1); lung adenocarcinoma (1); lung carcinoma (1); Lymphadenopathy (1); myelodysplastic syndrome (1); oropharyngeal squamous cell carcinoma (1); osteosarcoma (1); pancreatic cancer (1).